OR11G2 (olfactory receptor family 11 subfamily G member 2)
Description:
Odorant receptor.
Synonyms: OR14-34
Gene: Protein-coding gene on chromosome 14 (20,190,896 to 20,201,075, forward strand). Ensembl gene ENSG00000196832.
Subcellular location: Cell membrane
Pathways (Reactome):
Sensory Perception: Expression and translocation of olfactory receptors
Genetic constraint (gnomAD): Loss-of-function variants: 8 observed, 6.63 expected, observed/expected ratio (o/e) 1.21, 90% interval 0.69 to 1.86. That is too few expected variants to judge how well the gene tolerates losing a copy. Missense variants: 393 observed, 387.49 expected, observed/expected ratio (o/e) 1.01, 90% interval 0.93 to 1.1. Synonymous variants: 153 observed, 147.06 expected, observed/expected ratio (o/e) 1.04, 90% interval 0.91 to 1.19.
Homologues: Orthologues: chimpanzee OR11G2 (98% identical), dog OR11G2 (83% identical), rabbit OR11G2 (79% identical), mouse Or11g1 (78% identical). Paralogues in human: OR11H12 (61% identical), OR11H6 (61% identical), OR11H4 (60% identical), OR11H1 (60% identical), OR11H2 (60% identical), OR11H7 (59% identical), OR11A1 (46% identical), OR9G1 (41% identical), OR9A4 (40% identical), OR10X1 (39% identical), OR9A1P (39% identical), OR9A2 (39% identical), and 21 more.
Diseases named in the same sentence as OR11G2 in open-access papers:
OR11G2 is named in the same sentence as 1 disease in open-access papers, as found by Europe PMC text mining. Sharing a sentence is not in itself a finding about the gene and the disease.
OR11G2 shares sentences with these, for which no sentence is quoted: tumours (1 paper).